ARG1 (arginase 1)
Diseases named in the same sentence as ARG1 in open-access papers (continued):
Sharing a sentence is not in itself a finding about the gene and the disease.
eosinophilia (4 papers, 2018 to 2021). "We have previously shown that overexpression of OSM induces ECM accumulation and accumulation of arginase-1+ (Arg1) alternatively activated (AA/M2-like) macrophages, which was associated with eosinophilia and a Th2-like skewed cytokine profile in lungs of C57Bl/6 mice." (PMID 32471168, 2020). "Arginase production within the infection-expanded Mφ pool was not significantly different in tissue BALB/c eosinophilia-deficient mice compared with WT, adjudged by arginase activity or Mφ-specific arg1 transcripts." (PMID 29547639, 2018).
Hepatic steatosis (4 papers, 2016 to 2023). Steatosis is a term used to denote lipid accumulation within hepatocytes. "Some of the modifications include improvement in insulin sensitivity and glucose tolerance, decrease in body weight, decrease in hepatic steatosis, white adipose tissue (WAT) beigeing, and an increase in WAT eosinophils and M2 macrophages with increased expression of M2 markers (Ym1 and Arg1)." (PMID 38044996, 2023).
lymph node metastasis (4 papers, 2020 to 2025). "Plasma exosomal Arginase-1 (Arg-1) is associated with lymph node metastasis and poor prognosis, whereas intratumoral Arg-1 correlated with better outcomes." (PMID 41439998, 2025). "Patients with high Arginase-1 levels in these exosomes had lymph node metastasis and poor prognosis." (PMID 38001706, 2023). "High Arg-1 and GPC-3 levels, tumor grade, lymph node metastasis, vascular invasion, and TNM stage were risk factors associated with ICC progression." (PMID 34715880, 2021). "In humans, IL-10 serum levels increase over time during CRC progression, correlating with poor prognosis, while high levels of ARG-1 were associated with stage III–IV CRC tumors and lymph node metastasis." (PMID 33036138, 2020).
metabolic syndrome (4 papers, 2020 to 2024). A cluster of metabolic risk factors for CARDIOVASCULAR DISEASES and TYPE 2 DIABETES MELLITUS. "High expression of ARG1 was observed in HCV-positive HCC, while it was low in tumors associated with metabolic syndrome/NASH." (PMID 37760534, 2023). "The study found that there is a strong correlation between low ARG1 expression and poorly differentiated tumors, higher pathological stage, and decreased patient survival, particularly in those with metabolic syndrome/T2DM." (PMID 37760534, 2023). "In both metabolic syndrome/NASH and HCV-associated patients, significant correlation of ARG1 suppression and higher pathological stage was detected (p = 0.02 and p = 0.04, respectively)." (PMID 33092030, 2020). "Decreased expression of Arg1 and concomitant accumulation of arginine could be the feature of hepatocarcinoma cells during non-alcoholic steatohepatitis and metabolic syndrome." (PMID 38920664, 2024). "Clinicopathological analysis demonstrated significant correlation of negative ARG1 expression with poor tumor differentiation (p = 0.04) in human metabolic syndrome/NASH-associated but not in HCV+ HCCs." (PMID 33092030, 2020). "ARG1 expression could be demonstrated to be high in HCV+ HCC, but low in metabolic syndrome/NASH-associated tumors." (PMID 33092030, 2020).
multiple sclerosis (4 papers, 2012 to 2025). A progressive autoimmune disorder affecting the central nervous system resulting in demyelination. "Arg1 has also been shown to be specifically expressed by infiltrating myeloid cells in the central nervous system in models of spinal cord injury and multiple sclerosis." (PMID 41445743, 2025). "Furthermore, we also found that the oligodendrocyte-specific gene transcript marker Mog, which was elevated in Arg1 deficient APP mice in this study, was previously identified as a critical CNS-specific autoantigen responsible for demyelination in multiple sclerosis." (PMID 34046031, 2021).
myocardial ischemia (4 papers, 2017 to 2026). A disorder of cardiac function caused by insufficient blood flow to the muscle tissue of the heart. "Eight genes (Aif1, Apoe, Arg1, Col1a1, Gpx7, Hmox1, Mmp14, and Sirpa) were significantly differentially expressed in the rat myocardial ischemia-reperfusion model." (PMID 36826575, 2023). "Interestingly, six out of the seven most differentially expressed IZ genes (IL8, ARG1, S100A12, CTSL, IL1R2, S100A8) identified in our study have been previously reported in myocardial ischemia, confirming the validity of our chip analysis." (PMID 28977827, 2017).
ovarian tumor (4 papers, 2018 to 2024). "We further investigated the M2-like macrophages in ovarian tumor by IHC analysis for ARG1, a hallmark of alternatively activated macrophages; there was a significant decrease after ABBV-075 and AVA treatment (p < 0.001)." (PMID 35094142, 2022). "Next, immunohistochemistry was used to evaluate ARG1 expression in 84 primary ovarian tumors and in normal ovary epithelial tissues that were used as controls." (PMID 31278254, 2019). "To determine if DDR2-dependent (Arg1-dependent) polyamine production specifically could contribute to ovarian tumor cell invasion, we added exogenous spermidine or putrescine to CM from Ddr2-depleted CAFs and repeated the Boyden-chamber Matrigel invasion assays." (PMID 37996700, 2024). "In human ovarian tumor CAFs, SNAIL protein was detected at the promoter region of the human Arg1 gene, while in Ddr2-depleted CAFs, there was less SNAIL detected." (PMID 37996700, 2024). "In sum, these data indicated that the presence of DDR2 in omental ovarian tumor CAFs controlled polyamine production, likely through DDR2-regulated Arginase-1 production." (PMID 37996700, 2024). "To determine if DDR2 regulates Arg1 expression and arginase activity in omental CAFs in vivo, we made use of CAFs from the mouse ID8TB−/− syngeneic ovarian tumor model." (PMID 37996700, 2024). "Flow cytometry revealed that 85.1% of CD33+ cells were confined to the CD33+CD11b+LIN− HLA-DR−/low type in ovarian tumor samples, and these cells expressed high levels of Arginase 1 regardless of HLA-DR expression." (PMID 29703902, 2018). "CM from Arg1-depleted CAFs did not support ovarian tumor cell invasion through Matrigel." (PMID 37996700, 2024).
peritonitis (4 papers, 2016 to 2021). Inflammation of the peritoneum (tissue that lines the abdominal wall and covers most of the organs in the abdomen). "Arginase-1 is expressed by CD11bhigh macrophages during the early phase of resolution of peritonitis." (PMID 32625094, 2020). "The upregulation of MR, RELMα and Arg1 supported that M2 polarization is elicited on day 6 in this sterile peritonitis model." (PMID 27731330, 2016). "In this peritonitis model, mRNAs obtained from whole peritoneal white blood cells showed upregulation of M2 markers Arg1 and MR, and little upregulation of M1 markers iNOS and TNF-α." (PMID 27731330, 2016). "Indeed, relative expression level of Arg1 to a control house keeper gene (GAPDH) in these peritoneal-elucidated cells at healing stage of peritonitis was as high as that in in vitro-activated M2MΦs by recombinant IL-4." (PMID 27731330, 2016). "CDC-EVs enhance the Arg1/Nos2 ratio in macrophages in vitro and reduce MI size more than MSC-EVs and suppress inflammation during acute peritonitis in vivo." (PMID 33883598, 2021).
rheumatoid arthritis (4 papers, 2020 to 2024). A chronic, systemic autoimmune disorder characterized by inflammation in the synovial membranes and articular surfaces. "An opposite phenomenon of decreased serum levels of Arg-1/arginase activity was observed in the case of exacerbation of rheumatoid arthritis, while higher values were observed in the remission phase." (PMID 38592313, 2024).
sarcoma (4 papers, 2016 to 2024). A usually aggressive malignant neoplasm of the soft tissue or bone. "Similar to the other sarcomas expression of ARG2 was highest, with modest expression of ARG1 and NOS2 genes." (PMID 28969007, 2017). "In our attempt to check a panel of suppressive molecules in the gene level, it was found more or less downregulation of Arginase 1, iNOS2, STAT3, IL-10, IDO, MMP9 and TGFβ in MDSCs from NLGP-treated surgically sarcoma removed mice." (PMID 28414726, 2017).
Anxiety (3 papers, 2020 to 2024). Intense feelings of nervousness, tension, or panic often arise in response to interpersonal stresses. "The Arg1 insufficiency in APP mice precipitated more behavior impairment evidenced by more anxiety, more exploratory behavior, and decreased fear associated memory." (PMID 33519806, 2020).
Cachexia (3 papers, 2020 to 2025). Severe weight loss, wasting of muscle, loss of appetite, and general debility related to a chronic disease. "In cancer patients, we found an association between ARG1 expression and accelerated weight loss and reduced survival, further supporting a role of ARG1-producing cells in cachexia pathogenesis." (PMID 40474277, 2025). "If restricted arginine availability underlies these early events, targeting ARG1 could offer new opportunities for developing early interventions that address the onset of cachexia before wasting becomes clinically evident." (PMID 40474277, 2025). "Our findings indicate that ARG1-mediated degradation of intramuscular arginine may be an important mechanism for loss of muscle function in cachexia patients." (PMID 40474277, 2025). "We hypothesized that ARG1 expressing myeloid cells cause arginine deficiency in muscle tissue during cachexia and that this leads to compromised mitochondrial capacity and increased catabolic activity." (PMID 40474277, 2025). "Together, our findings point to a mechanism for cachexia which depends on expansion of ARG1-expressing myeloid cells, local restriction of arginine, loss of mitochondrial capacity and induced catabolism in skeletal muscle cells and in the heart." (PMID 40474277, 2025). "Our findings suggest that ARG1-mediated degradation of arginine may contribute to cachexia pathogenesis." (PMID 40474277, 2025). "We confirmed that the ATMs collected from the cachexia model were M2 polarized as well (Arg1+)." (PMID 38657734, 2024).
Chagas disease (3 papers, 2018 to 2021). A parasitic infection caused by Trypanosoma cruzi. "Because this arginase inhibition resulted in a decreased susceptibility to experimental Chagas disease our study supports in summary the conclusion that IL-13/IL-4Rα-driven Arg-1 expression contributes to the permissiveness of the host to T. cruzi infection." (PMID 30555475, 2018). "In experimental Chagas disease, however, it has been only shown that Arg-1 positive myeloid-derived suppressor cells (MDSC) infiltrate the heart of T. cruzi infected mice during the acute phase of the disease and that the degree of this infiltration correlates with the tissue parasite load." (PMID 30555475, 2018). "Both, Arg-1 and AAM undermine macrophage effector functions against intracellular parasites and are therefore implicated in the susceptibility to infection with Trypanosoma cruzi, the causative agent of Chagas' disease." (PMID 30555475, 2018). "In summary, we here give evidence that IL-4Rα-induced Arg-1 mediates susceptibility to acute experimental Chagas disease by several - mutually not exclusive - mechanisms downstream of Arg-1 including L-arginine depletion in MDSCs and AAM and polyamine synthesis." (PMID 30555475, 2018). "Thus the authors discuss that IL-4Rα-induced Arg-1 mediates susceptibility to acute experimental Chagas disease by several - mutually not exclusive - mechanisms downstream of Arg-1 including L-arginine depletion in MDSCs and M2 macrophages and polyamine synthesis." (PMID 34513737, 2021).
Cirrhosis (3 papers, 2021 to 2023). A chronic disorder of the liver in which liver tissue becomes scarred and is partially replaced by regenerative nodules and fibrotic tissue resulting in loss of liver function. "Examination of clinical samples in tissue microarrays (TMAs) that contained 88 cases of HCC and 58 cases of normal/cirrhosis samples showed significantly lower expression of ARG1 in HCC." (PMID 36256480, 2022).
citrullinemia (3 papers, 2018 to 2025). Citrullinemia is an autosomal recessively inherited disorder of urea cycle metabolism and ammonia detoxification characterized by elevated concentrations of serum citrulline and ammonia. "Firstly, physicians have to wait for results of chromatography of amino acids (CAA) to rule out citrullinemia, arginase 1 or argininosuccinate lyase deficiency before citrulline supplementation can be initiated." (PMID 37480106, 2023). "By contrast, UCDs caused by cytosolic enzyme deficiencies are treated differently; citrulline is not recommended for individuals with argininosuccinate lyase deficiency and citrullinemia, and supplementation with arginine is not recommended for arginase 1 deficiency." (PMID 37480106, 2023).
cognitive deficits (3 papers, 2022 to 2023). "As in mice, ARG1-deficient individuals show neurological problems evidenced by progressive neurological and cognitive impairment leading to various degrees of intellectual disability." (PMID 37169859, 2023). "Supporting this, microglial Arg1 knockout results in impaired neuronal plasticity and cognitive deficits in mice." (PMID 37169859, 2023). "In a recent paper, ARG-1 microglial conditional knockout mice display impaired neuronal plasticity and cognitive deficits." (PMID 36104346, 2022).
colorectal tumors (3 papers, 2023 to 2025). "In colorectal tumor models, MDSCs suppress infiltration of CD8+ T cells and NK cells by upregulating arginase-1 (Arg1) activity." (PMID 40969768, 2025). "We also found reduced arginase 1 (Arg1) and COX2 expression in colorectal tumors that lack GSDMD, supporting the notion that GSDMD mediates the recruitment of MDSCs to tumors." (PMID 38898209, 2024).
dengue (3 papers, 2010 to 2025). "We therefore set out to investigate associations between endothelial function (reactive hyperemic index [RHI]), plasma levels of l-arginine, ADMA, and arginase-1, in patients with dengue compared with other febrile illness (OFI) at serial time-points during the evolution of the acute illness." (PMID 28673038, 2017). "Considering early illness (days 1–3) compared to follow-up (day >13), dengue patients had lower l-arginine levels (P < .001) and l-arginine-to-ADMA ratio (P < .001), and higher arginase-1 levels (P = .004)." (PMID 28673038, 2017).
gastritis (3 papers, 2019 to 2025). Inflammation of the stomach. "A different model, designed to predict cancer or preneoplasia vs. healthy or gastritis, yielded an even higher mAUROC of 83.9% (73.9–93.9% (95% CI)) and was based on the plasma concentrations of ARG1, HPT, CA2, MAN2A1, and LBP." (PMID 41155404, 2025). "ARG1 was shown to be upregulated in gastric mucosa of patients with inactive gastritis." (PMID 37597422, 2023). "The best model for gastritis vs. non-gastritis classification combined H. pylori status with the plasma concentrations of ARG1, KRT14, and F13A1, yielding an mAUROC of 82.2% (64.1–99.9% (95% CI))." (PMID 41155404, 2025). "The analysis of the gene expression of ARG1, ARG2, and NOS2 was performed in the patients with chronic active gastritis, chronic inactive gastritis, no gastritis, or the control group." (PMID 31320834, 2019).
graft versus host disease (3 papers, 2013 to 2022). An immune system disorder that occurs after allogeneic hematopoietic stem cell transplant and is a reaction of donor immune cells against host tissues. "As such, peg-arginase 1 extends the survival of mice undergoing bone marrow transplantation and delays the appearance of graft versus host diseases, whereas enhancing the growth of Listeria." (PMID 28223985, 2017). "The direct contribution of MDSCs to in vivo T cell suppression in T cell-mediated diseases has remained largely uninvestigated, although, recently, ARG1 has been shown to limit graft versus host disease (GVHD) in mice." (PMID 23423530, 2013).
intestinal infection (3 papers, 2023 to 2024). "MMs respond by inducing Arginase 1 (Arg1) expression, while Tnf-gene expression remains unchanged upon intestinal infection." (PMID 39519291, 2024). "The protective effect of Arg-1 on neurons after intestinal infection was proved by hybridization between LysMCre mice and Arg-1flox/flox mice." (PMID 37138874, 2023). "Using two established mouse models, gastrointestinal infection with E. coli O157:H7 and intraperitoneal injection with Shiga toxin 2, elevated circulating arginase 1 and arginase activity were demonstrated and correlated with biomarkers related to hemolysis, such as LDH and the heme scavenger A1M." (PMID 38178089, 2024). "Th2 is a major source of IL-4, while IL-4 and IL-13 together coordinate alternative activation of macrophages, including upregulation of Arg-1, which may play a protective role against neurons during intestinal infections." (PMID 37138874, 2023).
keloid (3 papers, 2022 to 2025). An irregularly shaped, elevated mark on the skin caused by deposits of excessive amounts of collagen during wound healing. "We observed that human fibrotic tissues (hypertrophic scar and keloid) have higher expression of Arg1, OAT and PYCR1 than normal skin." (PMID 37752116, 2023). "Only IL-22, transforming growth factor-β, and arginase-1 exhibited significant higher levels in keloid scars." (PMID 35409053, 2022). "Only IL-22, TGF-β, and arginase-1 exhibited significantly higher levels in keloid scars." (PMID 39799030, 2025). "Biopsies from normal and keloid scars were collected and the mRNA expression of several growth factors and cytokines were determined: TGF-β, fibroblast growth factor, IL-33, IL-22, arginase-1, arginase-2, inducible nitric oxide synthase, vasoactive intestinal peptide, and its receptor." (PMID 39799030, 2025).
leishmaniasis (3 papers, 2011 to 2026). Infectious disease that is transmitted through the bite of hematophagous female phlebotomine sand flies. "We chose to analyze these two molecules because iNOS expression is generally associated with NO production and parasite control, while Arg-1 is associated with susceptible hosts and parasite survival in leishmaniasis." (PMID 40631203, 2025). "High expression of Arg1 is associated with the formation of chronic nonhealing lesions in leishmaniasis and is thought to cause a local depletion of l-arginine, thus inhibiting local Th1 activity." (PMID 21585399, 2011). "The expression of iNOS, arginase-1 and PD-1 was higher in the PBMC of dogs with leishmaniasis." (PMID 41623056, 2026).
Mycobacterium infection (3 papers, 2015 to 2019). Infections with bacteria of the genus Mycobacterium. "Together, these data demonstrate that Arg1 is induced through an IL-4Rα-independent pathway and is only expressed after a well-established Mycobacterium infection in macrophage cell-specific IL-4Rα deficient mice." (PMID 25790379, 2015). "Mycobacterium infection induces Wnt6 expression and promotes anti-inflammatory phenotype of macrophages through Arginase-1 expression." (PMID 31736969, 2019). "On the other hand, Qualls and co-workers found that macrophages after mycobacterium infection expressed arginase-1 through the TLR pathway." (PMID 27588757, 2016). "However, we have limited information on the induction of Arg1 following mycobacterial infections." (PMID 25790379, 2015).
osteoarthritis (3 papers, 2021 to 2025). A noninflammatory degenerative joint disease occurring chiefly in older persons, characterized by degeneration of the articular cartilage, hypertrophy of bone at the margins and changes in the synovial membrane. "The RT-PCR data manifested that the expression of M1 macrophage markers (TNF-α, IL-1β, and iNOS) were significantly upregulated, while the expression of M2 macrophage markers (IL-10 and Arg-1) was significantly downregulated in synovial tissues of osteoarthritis patients." (PMID 34652255, 2021).